ZNF485 (zinc finger protein 485)
Description:
May be involved in transcriptional regulation.
Tractability: PROTAC: ubiquitination databases record sites on it.
Gene: Protein-coding gene on chromosome 10 (43,606,413 to 43,617,904, forward strand). Ensembl gene ENSG00000198298.
Subcellular location: Nucleus
Pathways (Reactome):
Gene expression (Transcription): Generic Transcription Pathway
Gene Ontology:
Molecular function: protein binding; DNA-binding transcription activator activity, RNA polymerase II-specific; RNA polymerase II cis-regulatory region sequence-specific DNA binding; DNA-binding transcription repressor activity, RNA polymerase II-specific; sequence-specific DNA binding
Biological process: regulation of transcription by RNA polymerase II; negative regulation of transcription by RNA polymerase II; positive regulation of transcription by RNA polymerase II; regulation of DNA-templated transcription
Cellular component: nucleus; nucleoplasm
Genetic constraint (gnomAD): Loss-of-function variants: 7 observed, 10.38 expected, observed/expected ratio (o/e) 0.67, 90% interval 0.38 to 1.26. The upper end of that interval is the gene's LOEUF score, 1.26, which puts it in group 5 of 6, group 1 being the genes least tolerant of losing a copy. Missense variants: 474 observed, 535.95 expected, observed/expected ratio (o/e) 0.88, 90% interval 0.82 to 0.95. Synonymous variants: 184 observed, 185.14 expected, observed/expected ratio (o/e) 0.99, 90% interval 0.88 to 1.12.
Homologues: Orthologues: chimpanzee ZNF485 (99% identical), macaque ZNF485 (97% identical), dog ZNF485 (85% identical), Drosophila melanogaster CG18476 (26% identical), Drosophila melanogaster CG10669 (22% identical). Paralogues in human: ZNF808 (43% identical), ZFP62 (40% identical), ZNF721 (40% identical), ZNF648 (27% identical), ZNF664 (17% identical).
Diseases named in the same sentence as ZNF485 in open-access papers:
ZNF485 is named in the same sentence as 4 diseases in open-access papers, as found by Europe PMC text mining. Sharing a sentence is not in itself a finding about the gene and the disease. The quoted sentences say what the papers report.
breast carcinoma (1 paper, 2019). "For breast cancer, the number of KRAB‐ZNF‐positive samples was slightly different: (ZNF205 – 6/11, ZNF320 – 10/10, ZNF485 – 11/11, ZNF643 – 11/11, ZNF695 – 12/12, ZNF 707 – 10/10, and ZNF789 – 2/12)." (PMID 30444046, 2019). "In the breast cancer tissue panel (normal = 5, tumor = 43), we found that four KRAB‐ZNFs (ZNF205, ZNF273, ZNF485, ZNF695) were significantly upregulated in tumor tissue." (PMID 30444046, 2019). "Finally, these factors (ZNF273, ZNF485, ZNF695, ZNF643, and ZNF789), together with ZNF714, had significantly increased mRNA levels in the DNA methylation cluster 5 identified for breast cancer, which also coincides with the basal‐like subtype and the lowest overall DNA methylation level." (PMID 30444046, 2019).
lung carcinoma (1 paper, 2019). "In lung cancer tissue samples, KRAB‐ZNF staining was positive for at least four analyzed tumor samples (ZNF205 – 4/12, ZNF320 – 10/10, ZNF485 – 11/11, ZNF643 – 10/11, ZNF695 – 8/9, ZNF 707 – 10/11) and at least one sample from each set presented nuclear localization of a given factor." (PMID 30444046, 2019).
tumor (1 paper, 2019). "Within these 148 comparisons, significantly higher expression in normal tissues compared to tumor tissues was observed only in six cases (ZNF138 in KIRC and THCA, ZNF200 in THCA, ZNF273 in PRAD, ZNF485 in THCA, and ZNF789 in KICH)." (PMID 30444046, 2019).
ZNF485 also shares sentences with these, for which no sentence is quoted: cancer (2 papers).